RNU7-121P (RNA, U7 small nuclear 121 pseudogene)
Gene: Small nuclear RNA gene on chromosome 1 (39,723,566 to 39,723,627, reverse strand). Ensembl gene ENSG00000252413.
Homologues: Orthologues: chimpanzee U7 (100% identical), macaque U7 (97% identical). Paralogues in human: RNU7-82P (84% identical), RNU7-124P (82% identical), RNU7-11P (81% identical), RNU7-13P (81% identical), RNU7-35P (81% identical), RNU7-73P (81% identical), RNU7-7P (81% identical), U7 (81% identical), RNU7-111P (79% identical), RNU7-143P (79% identical), RNU7-176P (79% identical), RNU7-25P (79% identical), and 142 more.